ZFP91-CNTF (ZFP91-CNTF readthrough (NMD candidate))
Gene: Protein-coding gene on chromosome 11 (58,579,172 to 58,624,639, forward strand). Ensembl gene ENSG00000255073.
Genetic constraint (gnomAD): Missense variants: 568 observed, 644.59 expected, observed/expected ratio (o/e) 0.88, 90% interval 0.82 to 0.94. Synonymous variants: 304 observed, 241.19 expected, observed/expected ratio (o/e) 1.26, 90% interval 1.15 to 1.39.